MPO (myeloperoxidase)
Diseases named in the same sentence as MPO in open-access papers (continued):
Sharing a sentence is not in itself a finding about the gene and the disease.
infectious disease (15 papers, 2011 to 2025). A disorder directly resulting from the presence and activity of a microbial, viral, or parasitic agent in humans. "Although previous studies have suggested a potential role for MPO in infectious diseases, systematic investigations into its association with H. pylori infection risk remain limited." (PMID 40943779, 2025). "The major causes of death in patients with MPO-ANCA-positive ILD were acute exacerbation (AE) of ILD (10–25.5%), chronic progressive fibrosing ILD (PF-ILD) (7.8–19%), infectious disease (19.2–20%), and diffuse alveolar hemorrhage (DAH) (4.3–30%)." (PMID 35807120, 2022). "Taken together, these findings suggest that clinicians should create a decision-making strategy for the treatment of MPO-ANCA-positive ILD with an awareness of the presence of these four major causes of death (i.e., AE of ILD, PF-ILD, infectious disease, and DAH)." (PMID 35807120, 2022). "This hinders the use of MPO as an antimicrobial agent in treating infectious diseases." (PMID 35019674, 2022). "Thus, using MPO as a marker for infectious diseases, such as a significant bacteriuria and UTIs, could potentially be a useful diagnostic tool." (PMID 32442236, 2020). "In the absence of classic IE manifestations, such findings may point the clinician toward an auto-immune instead of an infectious disease, in particular when antineutrophil cytoplasmic antibodies (ANCAs) directed against proteinase-3 (PR3) or myeloperoxidase (MPO) are detected." (PMID 35732985, 2022).
liver (15 papers, 2015 to 2024). "Interestingly, in contrast to lung neutrophilia, the total neutrophil count in blood of wild-type and MPO deficient mice before and at different time points of LPS-induced lung inflammation did not significantly differ." (PMID 26998194, 2016). "MPO is a measure of hepatic neutrophil activity that reflects aseptic inflammation due to macrophage activation and neutrophil recruitment triggered by liver IR." (PMID 38954712, 2024). "In vivo SFN administration alleviates liver ischemia-reperfusion injury post HS/R and decreases MPO level." (PMID 35222401, 2022). "There was also a study showing that MPO promotes the development of lung neutrophilia and indirectly influences subsequent chemokine and cytokine production by other cell types in the lung, so the attenuation of MPO expression is notedly decreased in lung injuries." (PMID 36290622, 2022). "When GLP1 was administered (CD+GLP1+LT), it resulted in higher SOCS1 and SOCS3 expression than in the CD+LT group, and this was accompanied by less liver inflammation, evidenced by decreased levels of liver MPO, MDA, NO production, nitrotyrosine, and plasma vWF." (PMID 31835410, 2019). "Interestingly, the hepatic number of MPO-positive cells was lower in Ccr6-/- mice compared to wt after chronic liver injury (p<0.05)." (PMID 26691857, 2015). "At sites of inflammation, HOCl generated by MPO oxidizes Cys residues of TIMPs (Tissue inhibitors of metalloproteinases) abrogating TIMP-1 inhibitory activity during inflammation and dysregulating MMPs activation, thus affecting colorectal carcinogenesis." (PMID 28448444, 2017).
metabolic disorders (13 papers, 2012 to 2026). "Hence, prolonged MPO-mediated oxidative stress and metabolic disorder might be involved in the thermo-linked epizootic." (PMID 29382883, 2018). "In metabolic diseases, neutrophils release enzymes like myeloperoxidase and neutrophil elastase which promote insulin resistance and inflammation." (PMID 40846755, 2025). "Persistent inflammation, based on increased myeloperoxidase blood concentrations, was suspected to explain these altered exercise patterns with metabolic disorders." (PMID 37630785, 2023). "Uncontrolled MPO release exacerbates inflammation, oxidative stress and metabolic disorders, leading to atherogenesis." (PMID 36404308, 2022). "In conclusion, MPO deficiency attenuates the development of NASH and diminishes adipose tissue inflammation in response to a high fat diet, supporting an important role for neutrophils in the pathogenesis of metabolic disease." (PMID 23285030, 2012).
heart disease (12 papers, 2016 to 2025). "For MPO, we found higher serum levels among those with current smoking (126.8 versus 107.9 μg/L; p = 0.02) and heart disease (131.6 versus 108.2 μg/L; p = 0.02) in univariate analyses." (PMID 40940435, 2025). "In some heart diseases, the deletion or blocking of neutrophil-specific myeloperoxidase and peptidylarginine deiminase 4 has shown effectiveness." (PMID 33680285, 2021). "MPO levels in human serum have been proposed as a biomarker for several indications including heart disease." (PMID 26890638, 2016). "MPO and NGAL – activation markers for neutrophil granulocytes – were associated with heart disease." (PMID 40940435, 2025). "At the same time, myeloperoxidase (MPO) from neutrophils and macrophages has been confirmed to be a type of immune enzyme, and its drug inhibitor has a positive protective effect on arteriosclerotic heart disease (Soubhye, Van Antwerpen & Dufrasne, 2020)." (PMID 35186462, 2022). "In this study, cryolipolysis does not change/affect the concentration of MPO, by indicating how this procedure may not increase the cardiometabolic risk in people having altered plasma concentrations of MPO, such as those with heart disease." (PMID 36552200, 2022). "In multivariate analyses, subjects with heart disease had 22.1% (95% confidence interval 4.1%, 43.3%) higher MPO, 19.3% (7.8%, 31.9%) higher NGAL, and 23.2% (3.0%, 47.3%) higher EDN than subjects without heart disease." (PMID 40940435, 2025).
neurological diseases (10 papers, 2020 to 2025). "The underlying mechanism of MPO in these neurological diseases remains unclear." (PMID 33535986, 2021). "Therefore, the pharmacological benefit for MPO in preclinical settings of neurological disease models including inflammation-induced BBB dysfunction is following the ‘inhibit ROS toxifiers’ concept." (PMID 32050431, 2020). "The exact mechanism of MPO in these neurological diseases is not completely clear." (PMID 33573686, 2021).
immune diseases (9 papers, 2015 to 2025). "Here, we show that MPO protects against immune dysfunction by limiting a pathogenic programme that links T cell and neutrophil dysfunction." (PMID 35945238, 2022). "MPO activity is considered an effective diagnostic marker of oxidative damage and inflammation in OA and other immune diseases." (PMID 33927614, 2021). "The elevation of MPO activity is a major effective diagnostic tool for oxidative injury biomarkers and inflammatory markers in OA and other immune diseases." (PMID 33291821, 2020). "Indeed, elevated MPO during sμg may contribute to immune dysfunction." (PMID 33224136, 2020). "Two of 5 thrombinuria-negative patients with CresGN (all had pauci-immune disease) were positive for myeloperoxidase-ANCA." (PMID 25742509, 2015).
intestinal disease (9 papers, 2014 to 2025). "Unlike lactoferrin and calprotectin, MPO secretion in the stool is not affected by whether the child is breastfed such that variability in MPO may be more reflective of intestinal disease activity." (PMID 40440324, 2025). "The study measured myeloperoxidase (MPO) activity, an index of polymorphonuclear cell accumulation, and MDA, an indicator of lipid peroxidation (a molecular event involved in intestinal disorders)." (PMID 39858939, 2025). "Increased levels of myeloperoxidase (MPO), a neutrophil marker, correspond to the severity of inflammation in intestinal disease." (PMID 35682612, 2022). "The increased expression of myeloperoxidase (MPO), a neutrophil marker, corresponds to the severity of inflammation in intestinal diseases." (PMID 36499155, 2022). "Dietary CUR consumption has been reported to attenuate myeloperoxidase (MPO) activity and leucocyte infiltration, simultaneously downregulating the levels of proinflammatory cytokines in intestinal diseases connected with oxidative stress and chronic inflammatory processes." (PMID 34584616, 2021). "Gastric and intestinal ulcers induced by diclofenac (50 mg/kg) have been normalized using RJ at a dose of 150 mg/kg or 300 mg/kg via the increase of prostaglandin-2 (PGE-2) and COX-2 in the stomach tissues of mice, as well as reducing myeloperoxidase (MPO) and inducible nitric oxide synthase (iNOS)." (PMID 38337678, 2024).
peripheral neuropathy (8 papers, 2011 to 2025). A disorder affecting the peripheral nervous system. "Case 1, a 65-year-old man with MPO-AAV, presented with ILD with a Usual Interstitial Pneumonia (UIP) radiological pattern, cardiac dysfunction, ENT involvement, and peripheral neuropathy." (PMID 41438740, 2025).
hematologic malignancies (6 papers, 2018 to 2025). "Compared to T-ALL or B-ALL, super-enhancers associated with MPO were observed to be AML specific, while super-enhancers associated with ZFP36L2 were common to all three hematological diseases (AML, T-ALL, and B-ALL)." (PMID 35842703, 2022). "In addition, hematological disorders may also be related to polymorphisms in genes encoding xenobiotic-metabolizing enzymes, such as cytochrome P4502E1 (CYP2E1), myeloperoxidase (MPO), NAD(P)H:quinone oxidoreductase 1 (NQO1), and glutathione S-transferase (GST)." (PMID 30154939, 2018). "Other experimental potential biomarkers that are being tested in patients with hematologic malignancies are high-sensitivity CRP (Hs-CRP), interleukin-6 (IL-6), myeloperoxidase (MPO), fatty-acid-binding protein (FABP), glycogen-phosphorylase-binding protein (GPBP) and neuregulin-1 (NRG-1)." (PMID 39941907, 2025).
respiratory disease (6 papers, 2012 to 2023). "We analyzed 101 consecutive MPO-ANCA-positive patients with respiratory disease." (PMID 34732182, 2021). "Finally, a number of novel therapeutics which target neutrophil proteases, including MPO and elastase, have been effective in reducing neutrophil-driven inflammation in animal models of inflammatory disease and human respiratory disease respectively." (PMID 33469455, 2020).
vascular disorder (5 papers, 2016 to 2025). A general term used to describe any disease affecting blood vessels]. "MPO, a marker of leukocyte recruitment, is associated with the pathogenesis of a vascular disorders and inflammatory conditions like SLE." (PMID 40102640, 2025). "Recently, it was shown that ET formation promotes vasculopathies and externalization of ET-associated proteins such as histones and MPO leads to vascular barrier injury." (PMID 35591872, 2022). "Additionally, increased MPO concentration was previously observed in patients with FD, suggesting this could predict FD-associated vasculopathy, since MPO is a peroxidase enzyme secreted by neutrophils during degranulation." (PMID 38892211, 2024). "In OIR, the anti-Ly6G mAb reduced neutrophils in the blood and spleen, and myeloperoxidase, inflammation, and vasculopathy in the retina." (PMID 37958664, 2023). "Myeloperoxidase (MPO), a marker of leukocyte recruitment, is associated with pathogenesis of some vascular disorders and inflammatory conditions." (PMID 27648095, 2016).
adenocarcinoma (3 papers, 2020 to 2021). A common cancer characterized by the presence of malignant glandular cells. "The SAA/ALOX5 ratio was significantly increased in adenocarcinoma compared to control biopsies and this ratio strongly correlated with MPO-positive neutrophils in adenocarcinoma." (PMID 34203378, 2021).
gastrointestinal disease (3 papers, 2015 to 2023). A disease that occurs in the gastrointestinal system, excluding the hepatobiliary system. "Altered MPO levels in saliva were most commonly observed in patients with cardiovascular and gastrointestinal diseases." (PMID 37569455, 2023). "Altered MPO levels in saliva were most commonly found in patients with cardiovascular and gastrointestinal diseases." (PMID 37569455, 2023). "In conclusion, MPO could be altered in the saliva of patients with systematic diseases, especially cardiovascular or gastrointestinal diseases." (PMID 37569455, 2023). "According to our systematic review, myeloperoxidase could be altered in the saliva of patients with systematic diseases, especially cardiovascular or gastrointestinal diseases." (PMID 37569455, 2023).
brain diseases (2 papers, 2021 to 2023). "Gallic acid, on the other hand, has the potential to be an anti-inflammatory agent in inflammation-induced brain diseases, as evidenced by its ability to reverse the increase in NO and MPO induced by CdCl2." (PMID 36709339, 2023).
colon (2 papers, 2017 to 2019). "Taking it into consideration, more studies aimed to discuss the relationship of MPO-463G > A polymorphism and digestive system cancer, blood system cancer or the gene-gene or gene–environment interactions should be conducted to give a more deeper knowledge of this association." (PMID 28764808, 2017).
genetic disorder (2 papers, 2019 to 2023). "MPO deficiency is a genetic disorder with partial or complete absence of the phagocyte peroxidase MPO." (PMID 37954595, 2023).
psychiatric disorder (2 papers, 2025). A disorder characterized by behavioral and/or psychological abnormalities, often accompanied by physical symptoms. "In bipolar disorder type I, impaired MPO activity has been associated with oxidative stress and inflammation, underscoring its role in psychiatric disorders." (PMID 40401059, 2025). "Despite the critical role of MPO in oxidative stress, its levels have been investigated in psychiatric disorders only in a limited number of studies." (PMID 41300145, 2025). "Several studies have identified changes in MPO levels in psychiatric disorders." (PMID 41300145, 2025).
bone disorder (1 paper, 2017). "Alongside comparable plasma levels of bone disorder biomarkers—including serum calcium and phosphate, 25-OH vitamin D, 1,25-OH vitamin D, PTH, and FGF23—the average values of S100A12/ENRAGE, pentosidine, RAGE, and myeloperoxidase at baseline were very similar in the two study arms." (PMID 29362665, 2017).
hematopoietic tumors (1 paper, 2019). "We characterized 59 hematopoietic tumors using an immunohistochemistry (IHC) panel comprising the markers B220 (specific for B cells), CD3 (T cells), myeloperoxidase (myeloid cells), and CD138 (plasma cells)." (PMID 30926791, 2019).
mitochondrial disease (1 paper, 2025). "A combined urinary biomarker panel—including stress markers (GDF15, CYCS, and PRDX2), immune effectors (MPO and C4A), ECM proteins (COL1A1 and CCN2), and selected amino acids—could support diagnosis, patient stratification, and longitudinal monitoring in mitochondrial disease." (PMID 41373442, 2025).
MPO also shares sentences with these, for which no sentence is quoted: acute myocardial infarction (20 papers); end-stage renal disease (13); chronic periodontitis (10); leukocytosis (8); Parkinson’s (5); Allergy (4); hyperuricemia (4); juvenile idiopathic arthritis (4); memory impairment (4); sickle cell disease (4); Anorexia (3); cellulitis (3); focal segmental glomerulosclerosis (3); giant cell arteritis (3); glaucoma (3); hepatitis (3); leukocyte adhesion deficiency (3); membranoproliferative glomerulonephritis (3); minimal change disease (3); mixed phenotype acute leukemia (3); monoclonal gammopathy (3); neuromyelitis optica (3); osteoarthritis (3); pancreatic adenocarcinoma (3); Pancytopenia (3); prediabetes (3); rhinosinusitis (3); systemic inflammatory response syndrome (3); thrombotic microangiopathy (3); Abdominal obesity (2).
A further 262 diseases each share a sentence with MPO in 2 papers or fewer.